KRAS (KRas proto-oncogene, GTPase)
Diseases named in the same sentence as KRAS in open-access papers (continued):
Sharing a sentence is not in itself a finding about the gene and the disease.
non-small cell lung carcinoma (943 papers, 1996 to 2026). A group of at least three distinct histological types of lung cancer, including non-small cell squamous cell carcinoma, adenocarcinoma, and large cell carcinoma. "KRAS G12C-mutated non-small cell lung carcinoma (NSCLC), caused by a glycine-to-cysteine substitution at codon 12, is associated with poor prognosis and is now targetable with specific inhibitors." (PMID 41986521, 2026). "Background/Objectives: KRAS G12C mutations define a clinically actionable subset of solid tumors, particularly non-small cell lung cancer." (PMID 42122163, 2026). "Clinical trials report that the PD-1 antibody is more beneficial to patients with NSCLC (non-small cell lung cancer) having KRAS mutation than other patients." (PMID 40885393, 2025). "Sotorasib (AMG 510), a small molecule-targeted therapeutic that selectively inhibits the KRAS protein with the G12C mutation, is already approved by the regulatory authorities for the treatment of patients with KRAS G12C-mutated non-small-cell lung cancer." (PMID 40806294, 2025). "This drug is specifically designed for patients with non-small cell lung cancer (NSCLC) harboring the KRAS G12C mutation and functions by inhibiting the activity of the KRAS G12C protein, thereby impacting the growth and metabolism of cancer cells." (PMID 39744225, 2025). "Currently, sotorasib is approved in the EU at 960 mg daily for KRAS G12C advanced mutated non-small cell lung cancer, but the access has been withdrawn in France following the phase 3 (CodeBreak 200) results." (PMID 40573244, 2025). "Chemotherapy combined with immunotherapy is the preferred first-line treatment for adults with advanced KRAS-mutated non-small cell lung cancer (NSCLC)." (PMID 40296044, 2025). "The inhibition of the IL6/IL8 - JAK2 signaling can eliminate BRD4 phosphorylation and restore the sensitivity of tumors to BET inhibitors.In KRAS - mutated tumors, including non - small - cell lung cancer (NSCLC), an up - regulation of BCL6 has been observed." (PMID 39838405, 2025). "In non-small-cell lung cancer, KRas mutations frequently occur at codons Gly12, Gly13, and Gln61, leading to constitutive activation of the protein and contributing to oncogenesis." (PMID 40906088, 2025). "Background/Objectives: KRAS mutations are among the most prevalent oncogenic drivers in non-small cell lung cancer (NSCLC), with their impact on survival influenced by co-mutations." (PMID 41007704, 2025). "KRAS mutations are common in non-small cell lung cancer and are typically associated with poorer prognosis and fewer targeted treatment options." (PMID 40918860, 2025). "In lung cancer, mutated KRAS is a hallmark of non-small cell lung cancer (NSCLC), particularly adenocarcinoma, where it promotes tumor development and progression." (PMID 39786607, 2025). "The KRAS G12C mutation is a significant driver mutation in non-small cell lung cancer, with its unique biological properties and clinical relevance positioning it as a focal point for targeted therapies." (PMID 40303413, 2025). "Non-small cell lung cancer (NSCLC) patients harboring KRAS mutations are targeted using monoclonal antibody (mAb) or tyrosine kinase inhibitors (TKI) therapies." (PMID 39941857, 2025). "In KRAS-mutant non-small cell lung cancer, STK11 co-mutations are linked to reduced CD8+ T-cell infiltration and diminished PD-L1 expression." (PMID 41170373, 2025). "Clinical trials have demonstrated the significant efficacy of these inhibitors in non-small-cell lung cancer (NSCLC) harboring the KRAS G12C mutation, with improved progression-free survival and satisfactory safety profiles." (PMID 40427514, 2025). "Regarding other histologies, case #8 was a metastasic non-small cell lung cancer harboring a somatic KRAS G12A pathogenic variant." (PMID 40605011, 2025). "Three of the lines, LG0567-F671, 941728-121-R-J1, and HOP-62, are non-small-cell lung cancers harboring the KRAS G12C mutation." (PMID 40761343, 2025).
non-small cell lung carcinoma (continued). "KRAS is the most frequently mutated oncogene in human cancer, accounting for roughly 30% of non-small cell lung cancer (NSCLC) cases." (PMID 40788860, 2025). "The Kirsten rat sarcoma viral oncogene (KRAS) is a commonly mutated gene that is expressed in approximately 30% of patients with non-small cell lung cancer (NSCLC)." (PMID 40599804, 2025). "KRAS(G12C) mutations, present in approximately 13% of non-small cell lung cancer cases, represent a therapeutic target closely linked to immunotherapy resistance." (PMID 41584608, 2025). "Kirsten rat sarcoma viral oncogene homolog (KRAS) is one of the most frequently mutated genes in human cancer, including non-small cell lung carcinoma (NSCLC)." (PMID 41002380, 2025). "Kirsten Rat Sarcoma viral oncogene homolog (KRAS) is a frequently occurring mutation in non-small-cell lung cancer (NSCLC) and influences cancer treatment and disease progression." (PMID 39860023, 2025). "For example, the KRAS inhibitor sotorasib showed a 37% objective response rate in advanced or recurrent non-small cell lung cancer with KRAS p.G12C mutation." (PMID 39330006, 2024). "We will try to combine CT images, histopathology images, and genetic data to further improve the accuracy of KRAS gene mutation status prediction in non-small cell lung cancer." (PMID 38466735, 2024). "Mutated KRAS serves as the oncogenic driver in 30% of non-small cell lung cancers (NSCLCs) and is associated with metastatic and therapy-resistant tumors." (PMID 39271958, 2024). "A phase I trial demonstrated that sotorasib provided clinical benefit for KRAS G12C-mutated non-small cell lung cancers with an objective response rate of 32.2%, compared to only 7.1% for CRC, in patients with advanced solid tumors." (PMID 38407980, 2024). "Sotorasib and adagrasib have been widely used for the non-small cell lung cancer (NSCLC) patients harboring Kirsten rat sarcoma viral oncogene homolog (KRAS) G12C mutation." (PMID 39263575, 2024). "KRAS oncogenes are the most commonly mutated oncogenes in non-small cell lung cancer, but effective therapeutic strategies to target RAS-mutant cancers have proved elusive since direct inhibition of RAS proteins has proved difficult." (PMID 38558822, 2024). "KRAS mutations reduce the efficacy of erlotinib, as evidenced in patients with non-small-cell lung cancer where KRAS mutations led to diminished progression-free survival with erlotinib plus chemotherapy." (PMID 39770538, 2024). "TR102 (stage IIB, adenocarcinoma, 55-year-old male with occupation risk, smoker) has a KRAS missense mutation c.35G>T characterized as pathogenic with moderate impact on protein function and reported in non-small cell lung carcinoma." (PMID 38893104, 2024). "In 2021, a multi-channel and multi-task DL model proposed by Dong was used to predict EGFR and KRAS mutations in non-small cell lung cancer, with a prediction accuracy of about 70%." (PMID 38965599, 2024). "KRAS mutation is one of the most common oncogenic drivers in non-small cell lung cancer (NSCLC), accounting for ~ 25% of Caucasians and ~ 10% of Asians." (PMID 38291516, 2024). "In non-small cell lung cancer with KRAS mutations, the expression of arginine succinate synthetase is silenced, leading to a dependence on the arginine transporter SLC7A1 for arginine uptake from the extracellular environment." (PMID 39744129, 2024). "TBK1 induces anti-apoptosis in KRAS-mutated non-small cell lung cancer cell lines by activating NF-κB, and the TBK1-mediated pathway has been further investigated in various other KRAS-mutated tumors." (PMID 39161768, 2024). "An example of novel therapeutic agents successfully targeting specific KRAS mutations is sotorasib, the first FDA-approved drug for the treatment of KRAS G12C-mutated non-small cell lung cancer (NSCLC)." (PMID 38791980, 2024).
non-small cell lung carcinoma (continued). "Inhibition of ceramide kinase (CERK), a kinase associated with the generation of ceramide-1-phosphate (C1P), was explored in non-small cell lung cancer (NSCLC) cells harboring KRAS mutations." (PMID 38562143, 2024). "Oncogenic KRAS mutation in non-small cell lung cancer (NSCLC) patients confer a poor prognosis and a high risk of cancer recurrence." (PMID 38997257, 2024). "The particular status of KRAS mutation is critical to the response of non-small cell lung cancer (NSCLC) cells to sorafenib, a multi-target tyrosine kinase inhibitor." (PMID 38231277, 2024). "As one of the most common driver oncogenes in cancers, including non-small cell lung cancers (NSCLCs), KRAS mutation has long been considered as undruggable." (PMID 39594840, 2024). "KRAS (Kirsten rat sarcoma virus) mutations are commonly found in colorectal, pancreatic, and non-small-cell lung cancers." (PMID 39684787, 2024). "Remarkably, ctDNA levels are not solely dictated by tumor volume but are also influenced by genetic factors, including mutations in genes such as EGFR or KRAS in non-small-cell lung cancer." (PMID 38396722, 2024). "Two treatments targeting the KRAS G12C mutation have been approved for non-small-cell lung cancer, namely sotorasib (AMG510) and adagrasib (MRTX849)." (PMID 39594178, 2024). "We will review the clinical advances and challenges for patients with KRAS-mutated non-small cell lung cancer, with a focus on small molecule inhibitors." (PMID 39594840, 2024). "The etiology of some KRAS mutant cancers are distinct, e.g., G12C is the most common KRAS mutation in smoking-associated non-small cell lung cancer (NSCLC)." (PMID 38576709, 2024). "Two KRAS inhibitors, sotorasib and adagrasib, have recently been approved for the treatment of patients with advanced non-small cell lung cancer with the KRAS G12C mutation, while studies on their efficacy are still ongoing." (PMID 38397927, 2024). "A previous report demonstrated that the combination of a WEE1 inhibitor and a PARP inhibitor-induced replication stress and DNA damage in ovarian cancer and KRAS mutated non-small cell lung cancer." (PMID 37370065, 2023). "Adagrasib (KrazatiTM) is indicated for the treatment of metastatic or KRAS G12C-mutated locally advanced non-small cell lung cancer in adults who have received at least one prior systemic therapy." (PMID 36770706, 2023). "Previous reports have shown that IL-8 overexpression relies on oncogenic gene mutations, such as KRAS mutation, in non-small cell lung cancer." (PMID 37649607, 2023). "In a Phase Ib upgrade/expansion study, LXH254 was evaluated in conjunction with trametinib among patients grappling with advanced/metastatic non-small cell lung cancer harboring KRAS or BRAF mutations and NRAS-mutated melanoma (NCT02974725)." (PMID 38111008, 2023). "To further explore the clinical significance of the drug vulnerability discoveries from murine tumors, we investigated several KRAS mutated human non-small cell lung cancer lines." (PMID 36670102, 2023). "KRAS mutations occur frequently in advanced non-small cell lung cancer (aNSCLC); the G12C mutation is the most prevalent." (PMID 37069542, 2023). "Novel KRAS G12C allele-specific covalent inhibitors demonstrated a profound clinical impact in KRAS G12C-mutated non-small-cell lung cancer (NSCLC)." (PMID 37422534, 2023). "A meta-analysis reported similar observations when investigating EGFR and KRAS mutation status in matched primary tumors and distant metastasis of non-small cell lung cancer, which is also considered a tumor with a TMB." (PMID 38003476, 2023).
non-small cell lung carcinoma (continued). "Nonetheless, our research underscores the potential predictive value of KRAS mutations in determining responses to ICIs in cases of non-small cell lung cancer (NSCLC)." (PMID 37954616, 2023). "Sotorasib, which targets the KRAS G12C mutation, has shown an anticancer activity in patients with KRAS G12C mutated non-small cell lung cancer." (PMID 37046493, 2023). "Among RAS mutations, KRAS has the highest frequency and is present in almost 30% of non-small-cell lung cancer (NSCLC) patients." (PMID 36899885, 2023). "KRAS G12C mutation (mKRAS G12C) is the most frequent KRAS point mutation in non-small cell lung cancer (NSCLC) and has been proven to be a predictive biomarker for direct KRAS G12C inhibitors in advanced solid cancers." (PMID 37835787, 2023). "KRAS up-regulated PD-L1 through p-REK instead of the p-AKT pathway, and the PD-1 blocker or ERK inhibitor can rescue the antitumor function of T cells and reduce the survival rate of KRAS mutated non-small-cell lung cancer cells." (PMID 36688087, 2023). "LKB1 and KRAS are the third most frequent co-mutations detected in non-small cell lung cancer (NSCLC) and cause aggressive tumor growth." (PMID 36702816, 2023). "Three different isoforms of RAS proteins have been identified to date (KRAS, NRAS, HRAS) and mutations in KRAS are frequently found in human cancers, among which the Non-Small Cell Lung Cancer (NSCLC)." (PMID 36358848, 2022). "Of note, sotorasib was recently approved for locally advanced or metastatic KRAS G12C-mutated non-small-cell lung cancer patients who have received at least one prior systemic therapy." (PMID 35305098, 2022). "KRAS mutation is considered to be one of the most common genome variation in non-small cell lung cancer and is associated with a clinical background and pathological features." (PMID 36330448, 2022). "The Kirsten rat sarcoma viral oncogene homolog (KRAS) is the most common mutated oncogene in non-small cell lung carcinoma." (PMID 35877239, 2022). "Kirsten rat sarcoma (KRAS) mutation (KRASm) is associated with poor prognosis in non-small cell lung cancer (NSCLC) patients." (PMID 35713442, 2022). "KRAS is commonly mutated in non-small cell lung cancer (NSCLC); however, the prognostic and predictive impact of each G12 substitution has not been fully elucidated." (PMID 36452502, 2022). "Although KRAS-activating mutations represent the most common oncogenic driver in non-small cell lung cancer (NSCLC), various attempts to inhibit KRAS failed in the past decade." (PMID 35251972, 2022). "KRAS-mutated non-small cell lung cancer (NSCLC) accounts for 23–35% and 13–20% of all NSCLCs in white patients and East Asians, respectively, and is therefore regarded as a major therapeutic target." (PMID 36348317, 2022). "The aim of this review was to analyze the state-of-the-art of KRAS mutations in non-small-cell lung cancer by describing the biological structure of KRAS and exploring the clinical relevance of KRAS as a prognostic and predictive biomarker." (PMID 36012655, 2022). "KRAS is the most frequently mutated oncogene in non-small cell lung cancers (NSCLC), with a frequency of around 30%, and encoding a GTPAse that cycles between active form (GTP-bound) to inactive form (GDP-bound)." (PMID 35267628, 2022). "We and others have recently shown that KRAS mutations are connected to an enhanced dependency on one-carbon metabolism (1CM) in non-small cell lung cancer (NSCLC) and colorectal cancer." (PMID 35888776, 2022). "RAS mutation is the most frequent oncogenic alteration in human cancers and KRAS is the most frequently mutated, notably in non-small cell lung carcinomas (NSCLC)." (PMID 35406400, 2022).
non-small cell lung carcinoma (continued). "Based on non-small cell lung cancer datasets within cBioPortal, the landscape of KRAS G12C mutated tumors includes a complex landscape of co-altered genes 25,26." (PMID 34845311, 2021). "Recently, a promising new drug called Sotorasib (AMG 510), which is a novel KRAS inhibitor targeting the KRAS G12C mutation, was approved for treating patients with metastatic non-small-cell lung cancer harboring the KRAS G12C mutation." (PMID 34299137, 2021). "Two such inhibitors, sotorasib (AMG 510) and adagrasib (MRTX849), were recently evaluated in phase I-III trials for the treatment of non-small cell lung cancer with KRAS-G12C mutations, heralding a new era of precision oncology." (PMID 34607583, 2021). "The KRAS mutation has been shown to be one of the resistant mechanisms in MET-mutant non-small cell lung cancer patients receiving the c-MET tyrosine kinase inhibitor." (PMID 34439385, 2021). "Targeting KRAS p.Gly12Cys-mutations has recently been evaluated in non-small cell lung cancer (NSCLC) achieving durable clinical responses." (PMID 34771672, 2021). "KRAS is an oncogenic driver that appeared mutated in 30% of non-small cell lung carcinoma (NSCLC) and up to 50% of colon tumors." (PMID 33673558, 2021). "used different radiomic features, feature selection and classifiers of multimodal images to construct prediction models and observed their performance in predicting the mutation status of EGFR and KRAS in non-small cell lung cancer." (PMID 33596844, 2021). "The FDA granted breakthrough therapy designation to MRTX849 for the treatment of patients with KRAS G12C-mutated non-small cell lung cancer patients that has previously received systemic therapy." (PMID 34944853, 2021). "The silencing of deoxythymidilate kinase (DTYMK) in the context of LKB1 loss in LKB1/KRAS double mutant non-small cell lung cancer (NSCLC) has been shown to induce synthetic lethality." (PMID 35004265, 2021). "Studies of isogenic non-small-cell lung cancer cell lines harboring different KRAS G12C, G12D, or G12V mutations revealed differential metabolic signatures related to enhanced amino acid catabolism, altered lipid biochemistry and altered antioxidant program." (PMID 34233735, 2021). "Non-small cell lung cancer (NSCLC) patients harboring a KRAS mutation have unfavorable therapeutic outcomes with chemotherapies, and the mutation also renders tolerance to immunotherapies." (PMID 34073318, 2021). "Although historically considered to be undruggable, a particular KRAS mutation, the G12C variant, has recently emerged as an actionable alteration especially in non-small cell lung cancer (NSCLC)." (PMID 33777798, 2021). "KRAS is the most commonly mutated oncogene in human cancer, and is frequently mutated in cancer types associated with high mortality such as non-small cell lung cancer." (PMID 33514834, 2021). "Early identification of epidermal growth factor receptor (EGFR) and Kirsten rat sarcoma viral oncogene homolog (KRAS) mutations is crucial for selecting a therapeutic strategy for patients with non-small-cell lung cancer (NSCLC)." (PMID 34502160, 2021). "A better understanding of the role of KRAS and its different mutations has led to the development of specific small-molecule inhibitors able to target KRAS G12C, an oncogenic driver mutation in a number of cancers, including non-small cell lung cancer." (PMID 34064232, 2021). "Despite being the most frequent oncogenic alterations, KRAS mutations still represent a high unmet need in solid tumors, including non-small-cell lung cancer (NSCLC)." (PMID 34944952, 2021). "JUNIPER compared the efficacy and safety of abemaciclib, a selective cyclin-dependent kinase 4 and 6 inhibitor, with erlotinib in patients with non-small cell lung cancer (NSCLC) harboring a Kirsten rat sarcoma (KRAS) mutation." (PMID 33194700, 2020).